Y_RNA (Y RNA )
Gene: Miscellaneous RNA gene on chromosome 15 (74,983,274 to 74,983,376, reverse strand). Ensembl gene ENSG00000199580.
Homologues: Orthologues: chimpanzee Y_RNA (99% identical), pig Y_RNA (75% identical). Paralogues in human: Y_RNA (90% identical), RNY3 (89% identical), Y_RNA (89% identical), Y_RNA (88% identical), Y_RNA (87% identical), RNY3P1 (86% identical), Y_RNA (86% identical), RNY3P16 (85% identical), Y_RNA (85% identical), Y_RNA (84% identical), RNY3P14 (83% identical), Y_RNA (83% identical), and 97 more.